PLK4 (polo like kinase 4)
Diseases named in the same sentence as PLK4 in open-access papers (continued):
Sharing a sentence is not in itself a finding about the gene and the disease.
cancer (continued). "CFI-400945, a novel and highly selective polo-like kinase 4 (PLK4) inhibitor, causes dysregulation of centriole duplication, leading to defective mitosis, decreased proliferation, and cell death in cancer cells." (PMID 36750553, 2023). "Inactivation of PLK4 causes genomic instability, aneuploidy, and polyploidy in proliferating cancer cells." (PMID 36934096, 2023). "In particular, studies have been conducted on the biological function of PLK4 in cancer apoptosis and its association with cancer prognosis, but still limited in LUAD." (PMID 37760631, 2023). "Previous studies have identified associations between PLK4 and various diseases, especially cancers." (PMID 36620611, 2022). "The PLK4 gene is most commonly mutated in cancers through missense mutations, according to the cBioPortal database analysis." (PMID 36620611, 2022). "PLK4 gene alterations across several cancer types were primarily comprised of amplifications, mutations, and deep deletions." (PMID 36620611, 2022). "Studies suggest increased expression of PLK4 in various cancers and its association with tumorigenesis, cancer metastasis, resistance to chemotherapy and poor cancer prognosis." (PMID 35387563, 2022). "A wide variety of cancer types were found to harbor mutations, duplications, and amplifications of the PLK4 gene." (PMID 36620611, 2022). "PLK4 activity is required for centrosome amplification that can initiate tumorigenesis and has been considered a hallmark of cancer." (PMID 35670224, 2022). "Then we list the downstream targets of Plk4 and the hallmarks of cancer associated with these targets." (PMID 33777739, 2021). "PLK4 was also recently linked to cancer cell migration and invasion, consistent with our result that PLK4 inhibition mitigates vascular fibroblast migration." (PMID 33778212, 2021). "Plk4 has been identified as a master regulator of centriole replication, and its aberrant expression is closely associated with cancer development." (PMID 33777739, 2021). "Mounting evidence has implicated Plk4 in cancer progression, which can be mediated through Plk4-induced centriolar amplification, amongst other possible mechanisms." (PMID 32807875, 2020). "Increased Plk4 expression, which is a feature of many common human cancers, causes centriole overduplication, mitotic irregularities, and chromosomal instability." (PMID 32807875, 2020). "Observational studies of clinical cancers and xenografts indicate that high Plk4 expression is associated with aggressive behavior and treatment resistance." (PMID 32807875, 2020). "Centrosome amplification associated with PLK4 overexpression and its correlation with poor prognosis has been reported in many cancer types." (PMID 31035417, 2019). "PLK4 inhibition has induced apoptosis, senescence, and polyploidy in MB cells, thereby increasing the susceptibility of cancer cells to DNA-damaging agents." (PMID 31035417, 2019). "While overexpression of Plk4 causes centrosome amplification in cancer cells, insufficient amounts of Plk4 can trigger centriolar defects." (PMID 29757235, 2018). "Plk4 overexpression and overactivation are characteristics associated with many human cancers, and Plk4 is, therefore, considered a promising cancer target." (PMID 29757235, 2018). "We also demonstrated that PLK4 inhibition induced apoptosis, senescence and polyploidy in RT and MB cells, thereby increasing the susceptibility of cancer cells to DNA-damaging agents." (PMID 29340047, 2017). "Upregulation of PLK4 leads to centrosome amplification and extra centrosomes, promoting chromosome mis-segregation and leading to aneuploidy and chromosomal instability, a hallmark of cancer." (PMID 41092110, 2025). "Based on these studies, it appears that PLK4 inhibition may cause cancer reduction by promoting antitumor immunity." (PMID 40940791, 2025). "This demonstrated that a particular single-nucleotide polymorphism in PLK4 gene could alter susceptibility to cancer." (PMID 41488365, 2025).
cancer (continued). "Numerical chromosomal instability, such as that caused by PLK4 deregulation, might mediate responses of cancer cells to radiation treatment." (PMID 41092110, 2025). "Further, we have discussed PLK4 inhibitors and molecular pathways that could be associated with PLK4 and can open new avenues in cancer management." (PMID 41488365, 2025). "There is limited information on the molecular pathways associated with PLK4 in cancer pathogenesis." (PMID 41488365, 2025). "Additionally, we have summarized studies showing the association of PLK4 with multiple cancers and how its modulation affects cancer progression." (PMID 41488365, 2025). "Previous studies have inferred that PLK4 inhibition caused centrosome depletion, leading to delayed acentrosomal spindle assembly, while PLK4 stabilization resulted in centrosome amplification and cancer development." (PMID 39349439, 2024). "Yet, in megakaryocytes, PLK4 inhibition may cause thrombocytopenia—an undesired side effect in the context of cancer treatment." (PMID 39285247, 2024). "In this regard, given that aneuploidy is considered a cause of cancer development 45,46,67, our discovery of a ternary Vpr•VprBP•Plk4 complex and the ability of the complex to potentiate Plk4-mediated centriole duplication and induce aneuploidy are significant." (PMID 37645926, 2023). "Thus, PLK4 inhibition is currently being explored in TRIM37-implicated cancers as a way to trigger selective mitotic failure for cancer treatment." (PMID 39086683, 2023). "Furthermore, increased Plk4 expression has been linked to cancer metastasis and to chemotherapy resistance." (PMID 36797240, 2023). "In fact, Plk4 overexpression, as well as CA and centrosome structure abnormalities, have been already found in many types of tumors and shown to be significantly associated with poor clinical outcomes for cancer patients." (PMID 36797240, 2023). "PLK4 expression was associated with tumor prognosis according to the pan-cancer analysis." (PMID 36620611, 2022). "Abnormal expression of Plk4 has been observed in several cancers, it would be an interesting topic whether SNP or mutation of Plk4 gene in cancer will cause more frequency in aneuploidy." (PMID 33777739, 2021). "This could be a very interesting research project, because uncovering the association of SNP rs2305957 and dysregulated Plk4 in cancer might lead to development of a novel cancer biomarker or therapeutic target." (PMID 33777739, 2021). "Catalytic activity and protein turnover of PLK4 are tightly coupled in human cells, since changes in PLK4 concentration and catalysis have profound effects on centriole duplication and supernumerary centrosomes, which are associated with aneuploidy and cancer." (PMID 32501498, 2020). "Thus, our findings suggest that PLK1 and PLK4 inhibition underlies the activity of Poloppin in triggering mitotic arrest, and in preferentially killing cancer cells that express mutant oncogenic KRAS." (PMID 28807782, 2017). "Therefore, identifying factors that govern Plk4 transcription would probably be rewarding in understanding the causes or effects of centrosome amplification in cancer." (PMID 26439168, 2015). "Therefore, while PLK4 inhibitors could be beneficial for treating certain cancers, they may also pose a risk of inducing secondary malignancies." (PMID 40257113, 2025). "Therefore, strict regulation of PLK4 ensures that centriole duplication occurs precisely once per cell cycle, thereby avoiding potential abnormalities in centrosome number associated with chromosomal instability and cancer." (PMID 40710347, 2025). "Hence, inhibition of PLK4 can cause centrosome-related errors, such as centrosome amplification which leads to improper mitotic progression, genomic instability and subsequent cancer cell death." (PMID 38365710, 2024).
cancer (continued). "Interestingly, POLQ overexpression was associated with an increased somatic mutation load and PLK4 overexpression in diverse human cancers, while overexpressions of the nine TLS polymerases other than POLQ examined were associated with an increased somatic mutation load at much lower frequencies." (PMID 31137743, 2019). "Due to its importance in cancer development and progression, PLK4 represents an attractive target for the development of novel therapeutics." (PMID 42220890, 2026). "Improper PLK4 activity can lead to lethal chromosomal segregation issues in already dysregulated cancer cells." (PMID 40565600, 2025). "Research highlights the interaction between PLK4 and various signaling pathways in a variety of cancer models." (PMID 40940791, 2025). "It was further found that three sites of PLK4, including cg22112850, cg06015521, and cg26882168, were highly methylated, and the higher the methylation level, the better it was for cancer prognosis." (PMID 41488365, 2025). "Taken together, PLK4 inhibitors are currently being evaluated in both preclinical and clinical settings, showing potential for cancer management." (PMID 41488365, 2025). "As discussed in the previous section, PLK4 has emerged as a promising therapeutic target for cancer management." (PMID 41488365, 2025). "This highlights PLK4 as a possible mechanism of heavy metal-mediated cancer and provides a therapeutic target for future studies." (PMID 41488365, 2025). "Targeting the centriole duplication machinery therapeutically, particularly through the use of PLK4 inhibitors, shows great potential for developing future cancer therapies." (PMID 40710347, 2025). "For example, PLK4 inhibitors, which are key regulators of centriole duplication, are being investigated as potential cancer treatments to reduce centrosome amplification in tumours." (PMID 40710347, 2025). "Dysregulation of PLK4 can disrupt genomic integrity, contributing to tumorigenesis, thus making it a promising target for cancer management." (PMID 40940791, 2025). "This review discusses the existing knowledge on the role and function of PLK4 and its relationship with genomic instability and cancer." (PMID 41488365, 2025). "This review encapsulates the latest advancements in our understanding of centriole duplication and acentrosomal cell division in the context of TRIM37 amplification, positioning PLK4 as a compelling target for innovative cancer therapeutics." (PMID 40257113, 2025). "In the next section, we have summarized available PLK4 inhibitors studied in regulating cancer growth." (PMID 41488365, 2025). "Following the report of its depletion by RNA-silencing-induced apoptosis, PLK4 emerged as a promising target for cancer treatment." (PMID 40710347, 2025). "Functionally, PLK4 affects cancer cell proliferation, growth, motility, invasion, migration, epithelial-mesenchymal transition, apoptosis and other critical oncogenic processes." (PMID 41092110, 2025). "Below, we have discussed published literature on small-molecule inhibitors of PLK4 in cancer management." (PMID 41488365, 2025). "PLK4 protein expression was significantly upregulated in cancer tissues of breast ductal carcinomas as compared with the adjacent normal tissues." (PMID 41092110, 2025). "Some studies have shown that PLK4 overexpression triggers changes in skin tissues that are prerequisites for cancer development." (PMID 41488365, 2025). "PLK4 inhibitors are being explored as potential therapeutic agents for cancers that depend on functional centrosomes." (PMID 40257113, 2025). "For example, the overexpression of PLK4 can be sufficient to induce centriole amplification and cancer in mice." (PMID 38935637, 2025). "Further studies are needed to provide advanced insight into the molecular mechanisms of PLK4 in cancers." (PMID 41488365, 2025). "A comprehensive understanding of PLK4 regulation through ubiquitination is essential for developing effective cancer therapies." (PMID 40710347, 2025).
cancer (continued). "In this perspective article, we explore the emerging significance of PLK4 in hyperproliferative skin diseases including cancer." (PMID 40940791, 2025). "Sensitivity of cancer cells to PLK4 inhibition appears to be dependent on the levels of TRIM37 (Tripartite motif-containing protein 37) ubiquitin ligase." (PMID 41092110, 2025). "Downregulation of PLK4 with siRNA impaired the ability of HPV E7 to induce centriole overduplication in cancer cells." (PMID 41488365, 2025). "Studies have demonstrated that PLK4 inhibition either by genetic manipulation or using small molecule inhibitors impedes cancer growth and it is beneficial for cancer management." (PMID 40940791, 2025). "In the context of cancer, aberrant PLK4 expression compromises mitotic fidelity and centrosome homeostasis, exacerbates replication-associated DNA damage, and impairs the DDR efficiency, thereby promoting chromosomal instability and tumor progression." (PMID 40940791, 2025). "Growing evidence suggests a critical role of PLK4 in the development and progression of various cancers." (PMID 41092110, 2025). "The interplay of primary cilia and PLK4, particularly in cancer signaling, seems an interesting field for future investigation." (PMID 41488365, 2025). "Recent advances in the development of PLK4 inhibitors have opened new avenues for cancer management, particularly in malignancies characterized by high levels of chromosomal instability and/or PLK4 overexpression." (PMID 41488365, 2025). "We have also discussed the potential of PLK4 as a therapeutic target against cancer and the preclinical and clinical studies on PLK4 inhibitors in cancer." (PMID 41488365, 2025). "A direct role in cancer development has also been established in animal models exploiting conditional overexpression of PLK4 in all somatic tissues." (PMID 38552015, 2024). "Unsurprisingly, centrosome abnormalities are frequently found in cancer and forced centrosome overduplication by PLK4 overexpression, a key regulator of their biogenesis, has been reported to suffice to promote cancer formation in animal models." (PMID 39475598, 2024). "Recent studies have revealed that PLK4 induced centrosome amplification is not only present in cancer cells but is also necessary for generating multiciliated cells." (PMID 38388511, 2024). "Such widespread occurrence of PLK4-induced centriole rosettes, spanning from cancer to stem cells, underscores their importance in cell biology." (PMID 38388511, 2024). "The utilization of these compounds, particularly Rank 1, for cancer treatment and the inhibition of Aurora B and/or PLK-4 manifests as a primary claim in the patents." (PMID 38168595, 2024). "Among them, PLK4 is a pivotal regulator of tumor growth and metastasis, making it a therapeutic target for cancers." (PMID 38326803, 2024). "Considering the pros and counterarguments of using PLK4 as a biomarker of cancer invasiveness, we have to admit that numerous studies report the overexpression of PLK4 in different human cancers." (PMID 39329988, 2024). "Our results pave the way for the development of CRL4DCAF1-dependent PROTACs or molecular glue degraders to target PLK4 degradation as a novel modality for cancer therapy." (PMID 38490717, 2024). "More importantly, PLK4 was enriched in various cancers and promoted tumor proliferation, invasion, migration, and metastasis." (PMID 39349439, 2024). "The treatment of transformed cancer cell lines with the PLK4 inhibitor Centrinone B to decrease inherent CA and reverse CA-induced phenotypes has previously been demonstrated." (PMID 37772773, 2023). "In conclusion, our observations have important implications for understanding the potential link between Plk4 levels, cancer and tumor microenvironment, as well as clinical outcomes." (PMID 36797240, 2023).
cancer (continued). "Due to its role in controlling centriole duplication and its deregulation in multiple tumors, participating in tumorigenesis, metastasis and in the chemotherapy response, Plk4 has been put forward as a potential therapeutic target in cancer." (PMID 36797240, 2023). "Aberrant PLK4 expression is frequently observed in cancer and contributes to tumorigenesis and unfavorable patient prognosis." (PMID 37760631, 2023). "Dysregulation of PLK4 activity leads to abnormal centriole numbers, resulting in the formation of supernumerary centrosomes, genomic instability, and cancer development." (PMID 37760631, 2023). "Connecting this finding with bioinformatic data on PLK4, previous studies have reported a correlation between high PLK4 expression and poor prognosis in various cancer types." (PMID 37760631, 2023). "PLK4 is aberrantly expressed in cancer cells but normally has a low abundance and is only present in proliferating normal tissue." (PMID 36750553, 2023). "CFI-400945 was discovered as a cancer drug by targeting PLK4, which has a pivotal role in regulating centriole duplication." (PMID 36750553, 2023). "It is well known that PLK4, a serine/threonine protein kinase, is aberrantly expressed in cancer cells but normally has a low abundance and is only present in proliferating normal tissues." (PMID 36750553, 2023). "For example, CFI-400945, a potent Polo-like kinase 4 (PLK4) inhibitor, and RV-521, a viral fusion inhibitor, advanced into Phase II clinical trials for the treatment of human cancers and RSV infection, respectively." (PMID 36678857, 2023). "The Polo family serine threonine kinase (Plk4) expression is increased in a variety of cancers, including: breast, colorectal, prostate, and pancreatic cancers, and promotes cancer cell invasion and migration." (PMID 37026902, 2023). "Despite strong evidence of Plk4’s role in cancer and its therapeutic potential, it is still unclear how it contributes to tumorigenesis." (PMID 36797240, 2023). "We observed a significant increase on the capacity of these cancer cells to form mammospheres when treated with the conditioned media of Plk4-induced MCF10Ap53KO when compared to control condition." (PMID 36797240, 2023). "Consistent with the trend observed for PLK4 mRNA expression levels, the expression levels of PLK4 protein were also higher in proliferating tissues and cancer tissues." (PMID 36620611, 2022). "Then, we used the cBioPortal portal to analyze TCGA cancer datasets for different types of alterations in the PLK4 gene." (PMID 36620611, 2022). "As a critical regulator of cancer development, PLK4 has emerged as a therapeutic target for multiple cancers." (PMID 35670224, 2022). "Consistently, our results illustrated that PLK4 play a role in cancer cells through regulating PI3K/Akt activation." (PMID 35387563, 2022). "Secondly, in order to reveal the oncogenic mechanisms of PLK4 in pan-cancer, the top 100 PLK4 positively correlated genes in pan-cancer were collected for enrichment analysis." (PMID 36620611, 2022). "The first trailblazing work on the impact of Plk4 overexpression in cancer came from studies in Drosophila, showing that centrosome amplification cannot promote spontaneous tumors." (PMID 35269408, 2022). "The GO and KEGG enrichment analysis indicate that PLK4 were closely involved in tumor immune microenvironment, genome instability, and cell cycle progression in pan-cancer." (PMID 36620611, 2022). "Inhibition of PLK4 with small molecule inhibitors has been considered as a therapeutic option in cancers." (PMID 35053604, 2022). "According to these results, PLK4 mRNA expression levels were higher in cancer tissues than in normal tissues." (PMID 36620611, 2022).